PMS2 (PMS1 homolog 2, mismatch repair system component)
Diseases named in the same sentence as PMS2 in open-access papers (continued):
Sharing a sentence is not in itself a finding about the gene and the disease.
tumor (continued). "Replication error (RER) phenotyping of the tumor revealed a microsatellite stable (MSS) phenotype and, in terms of immunohistochemistry, persistent expression of hMLH1, hMSH2, hMSH6, and PMS2 proteins was observed." (PMID 36926521, 2023). "Tumor and subsequent germline analysis revealed that the patient inherited the familial POLE PV from his mother and had a de novo germline PMS2 PV c.2148dupC p.(V717Rfs*19)." (PMID 36291559, 2022). "In vivo growth of WHIM20, PMS2 mutant, ER+/HER2− PDX tumors xenografted into mouse mammary fat pads demonstrated a similar pattern of tumor regression in response to combination of lapatinib and fulvestrant but not in response to either treatment alone." (PMID 34011995, 2021). "MMR protein detection was retained in all original tumours except for CRC11, which lost PMS1 homolog 2, mismatch repair system component (PMS2) expression." (PMID 34572922, 2021).
tumor (continued). "At the same tumor, 4 cases were abnormal both for MLH1 and PMS2 and one case was abnormal for both MLH1 and MSH6." (PMID 34306129, 2021). "One poorly differentiated adenocarcinoma with mucinous features showed morphologic heterogeneity in addition to increased tumor intraepithelial lymphocytes and was found to have lost expression of MLH1 and PMS2." (PMID 28476018, 2017). "Immuno-histochemical staining for the proband's tumor cell showed that strong expression of the MLH1 and PMS2 with diffuse immunoreactivity." (PMID 28903413, 2017). "The data presented above provides evidence that APE1, NBN, PMS2, MGMT and PTEN mRNA expression levels have prognostic and predictive significance in adult tumours." (PMID 25026297, 2014). "The data presented in adult tumours provide compelling evidence for the role of APE1, NBN, PMS2, MGMT and PTEN in gliomagenesis." (PMID 25026297, 2014).
tumor (continued). "In our case, the decision to omit chemotherapy was informed by the tumor’s MMR-deficient profile (loss of MLH1 and PMS2), stage IIA classification (T4N0M0), and the absence of additional high-risk features beyond lymphovascular invasion." (PMID 40151739, 2025). "In order to analyze the immune activation profile, PMS2 wild‐type (PMS2WT), PMS2 knockout (PMS2KO), and PMS2 overexpression in PMS2KO cells (PMS2Rescd) were generated in both human SW480 and mouse CT26 tumor cells, both of which are considered as MSS CRC cell lines." (PMID 40344511, 2025). "PMS2 (p.E81*, VAF 0.465, NM_000535) was detected as a PGPV, whereas neither MSI-H nor high tumor mutational burden (TMB-high) was observed." (PMID 40335734, 2025). "On the other hand, if PMS2 expression is absent in both tumor and stromal cells, it typically indicates a more extensive MMR deficiency, suggesting an MSI-H status." (PMID 40519284, 2025). "Furthermore, the combination of PRMT5i with CPT‐11 elicited a dMMR‐like state and activated cGAS‐STING signaling in a PMS2‐dependent manner, which subsequently enhanced CD8+ T cell‐mediated anti‐tumor immunity and increased sensitivity to αTIGIT treatment." (PMID 40344511, 2025). "Another point worth discussing in this case is that the patient’s preoperative gastrointestinal biopsy and immunohistochemistry showed negative PMS2 expression in tumor cells and positive expression in stromal cells." (PMID 40519284, 2025). "Intragroup comparison revealed that the TMB of patients harboring the other three genes was greater than that of patients harboring PMS2 in the total population and in the non-CNS LS-related tumor group (p < 0.05)." (PMID 41261115, 2025). "In this particular case, the patient’s tumor cells were negative for PMS2, while stromal cells remained positive." (PMID 40519284, 2025). "In contrast, variants in STK11, PMS2, MUTYH, and RB1 were primarily classified as VUS and did not demonstrate an apparent relationship with tumor aggressiveness." (PMID 41595443, 2025). "The detection ratio of PMS2 in the Non-CNS LS-unrelated tumor group was significantly greater than that in the CNS LS-related tumor group (43.4% vs. 17.65%, p = 0.036) and Non-CNS LS-related tumor group (43.4% vs. 18.8%, p = 0.021)." (PMID 41261115, 2025). "In the Non-CNS LS-unrelated tumor group, MSH-H only existed in some samples with MLH1 variants and in 1 patient with a PMS2 variant." (PMID 41261115, 2025).
tumor (continued). "The tumor of this index case showed a normal expression of MLH1 and PMS2 proteins." (PMID 38843250, 2024). "The tumor was MSI-high and out of the four mismatch repair genes, only PMS2 was inactivated." (PMID 37386324, 2023). "In the present study, loss of PMS2 expression and MSI-H in tumor tissue of patient CR1 were determined, while non-neoplastic cells were immunopositive for PMS2." (PMID 37308967, 2023). "The three MLH1 methylated EOCRCs each showed loss of MLH1/PMS2 protein expression by IHC, showed high levels of MLH1 methylation in their tumours (β = 0.34, 0.42, 0.67) and did not have the BRAF p.V600E mutation or CIMP-high." (PMID 37270516, 2023). "Study indicates that tumors lacking the mismatch repair protein duo MLH1/PMS2 always have a lower TMB than those tumor lacking a different protein heterodimer, MLH2/MSH6." (PMID 35445008, 2022). "The fourth tumor had a complete loss of MLH1 and PMS2 staining and MLH1 promoter methylation was absent." (PMID 35877698, 2022). "This was illustrated by the additional germline PMS2 PV identified in a “screen-negative” individual with MLH1/PMS2 protein deficiency and positive MLH1 promoter methylation in her tumour." (PMID 33467402, 2021). "The MSI-H example shown (A-G) illustrates that MLH1 and PMS2 were not expressed in this tumor (E, G)." (PMID 32576892, 2020). "If there is no BRAF mutation in a tumor, performing further genetic tests for MLH1 and PMS2 germline mutations is recommended." (PMID 33027913, 2020).
tumor (continued). "The tumor from this patient is mismatch repair deficient (MMRD), with microsatellite instability (MSI‐H), negative MLH1/PMS2 immunohistochemistry and with MLH1 promoter hypermethylation (OMIM #120436)." (PMID 30827058, 2019). "The tumour was MSI-H, MLH1 and PMS2 deficient, and negative for BRAF V600E, but no pathogenic mutation was identified on next generation sequencing." (PMID 31647837, 2019). "This explains the MSI phenotype and the absence of nuclear expression of MLH1 and PMS2 in the tumor cells." (PMID 31104363, 2019). "Tumor tissue from one animal retained strong staining for MLH1 and PMS2." (PMID 30108684, 2018). "MLH1 expression was heterogeneous and PMS2 expression was lost and the tumor was also negative for MLH1 methylation." (PMID 28944238, 2017). "In case of immunohistochemical absence of either MLH1 or PMS2, or demonstrated microsatellite instability, tumor tissue should be tested for biallelic hypermethylation of the MLH1 promotor, which is indicative for sporadic non-LS-associated cancers." (PMID 28510097, 2017). "Commercial immunohistochemistry and microsatellite instability analysis showed absence of MLH1 and PMS2 protein expression and that the tumor was MSI-High." (PMID 25389437, 2014). "In addition, we analysed the expression of MLH1, PMS2 and MGMT in primary and recurrent GBM tumour samples obtained from patients with GBM recurrence during TMZ treatment." (PMID 24259277, 2013). "Relatively young patients without a strong family history who present a MSI-H tumor with loss of MLH1 and PMS2 protein expression are suggested as candidates for MLH1 germline epimutation screening." (PMID 20444249, 2010). "Previous studies of Pms2−/−;ApcMin mice have shown a primary role for Mlh1-Pms2 in GI tumorgenesis suppression but not tumor progression." (PMID 18551179, 2008). "Pathogenic germline nonsense mutations in PMS2 (rs63750451) and MSH6 (rs267608094) were found in 2 patients, however, there was no indication of dMMR in the patients’ tumours, as the tumour mutation burden in these samples was < 1 mutation/Mb." (PMID 40389436, 2025). "Tumours from two carriers of this variant were MSI-H and lacked PMS2 expression on IHC." (PMID 39334433, 2024).